BCL2L11 (BCL2 like 11)
Diseases named in the same sentence as BCL2L11 in open-access papers (continued):
Sharing a sentence is not in itself a finding about the gene and the disease.
tumor (140 papers, 2007 to 2026). "LOH-CNN, indicating wild-type allele loss with amplification of tumour suppressor losses, was observed in BCL2L11 and BARD1 for patients KAL0101 and N0073." (PMID 40064858, 2025). "BCL2L11 is a tumor suppressor, it is an important regulator of apoptosis; loss of the SMAD4 activity may disrupt DNA damage response and repair mechanisms and enhance genomic instability." (PMID 31540229, 2019). "AS-tDR-007872 was recognized as a diagnostic biomarker and a tumor suppressor for NSCLC with inhibitory effect on tumor cell proliferation, invasion, and migration, which is probably induced by targeting BCL2L11." (PMID 36782290, 2023). "BCL2L11 is involved in the intrinsic apoptosis pathway as a pro-apoptotic regulator and overexpression inhibited tumor growth and increased apoptosis induction." (PMID 37313172, 2023). "For example, significantly increased expression of BCL2L11 would lead to increased apoptosis and thus decreased tumor growth." (PMID 36078139, 2022). "BCL2L11 deletion/downregulation is found in many neoplasms and contribute to acquired drug resistance." (PMID 35754839, 2022). "MiR-106a targets proapoptotic Bcl-2-like protein 11 (BCL2L11) and acts as oncomiRNA and stimulates migration, invasion in vitro, and tumor growth in vivo." (PMID 34298609, 2021). "Bcl-2-like protein 11 (BCL2L11 or BIM) belongs to the B-cell lymphoma-2 (BCL-2) family proteins that play key roles in regulating apoptosis of tumor cells." (PMID 34722761, 2021). "We showed that the mRNA targets for lncRNA RP11-399O19.9 included a variety of tumor-associated genes, such as the apoptosis-related genes FAS, BCL2, and BCL2L11." (PMID 30984308, 2019). "We showed that these mRNA targets for lncRNAs in the ceRNA network included a variety of tumor-associated genes, such as the apoptosis-related genes FAS, BCL2, and BCL2L11 and the DNA repair gene BRCA1." (PMID 30984308, 2019). "We found that a variety of tumor progression-related genes were involved, such as apoptosis-related genes (FAS, BCL2, and BCL2L11) and a gene associated with DNA repair (BRCA1)." (PMID 30984308, 2019). "Using a panel of EBNA3KO viruses in BL31 BL-derived cells, EBNA3A and EBNA3C were found to cooperatively repress the tumour suppressor and pro-apoptotic BCL-2-family member BIM (Bcl-2-interacting mediator of cell death) encoded by BCL2L11." (PMID 29562595, 2018). "miR‐221 targets among other genes BCL2L11, which exhibits pro‐apoptotic properties, thereby suppressing tumor growth, as well as the gatekeeper PTEN." (PMID 29120535, 2018). "Subsequently, we assessed the effects of miR-24 or BCL2L11 in tumor growth by using mouse implanted tumor model." (PMID 26758252, 2016). "In the present study, miR-24 was found to be up-regulated while the expression of BCL2L11 was inhibited in tumor tissues of GC." (PMID 26758252, 2016). "In vivo experiments demonstrated that high level of miR-24 clearly accelerates while BCL2L11 overexpression strongly inhibits tumor growth." (PMID 26758252, 2016). "miR-106b and miR-93 abrogate TGFβ-induced apoptosis in GC cells by targeting the expression of BIM, encoding the pro-apoptotic protein BCL2-like 11, and thereby prevent apoptosis and cause tumor progression." (PMID 27322246, 2016). "In neuroblastoma cells, FOXO3 regulates cellular apoptosis by activating the two BH3-only proteins PMAIP1/Noxa and BCL2L11/Bim and sensitizes these tumor cells to chemotherapy-induced cell death by repressing the IAP-family member BIRC5/Survivin." (PMID 25261981, 2014). "In particular, EBNA3A and EBNA3C cooperate to repress the expression of the pro-apoptotic tumor-suppressor gene BCL2L11 (BIM) and the cyclin-dependent kinase inhibitor gene CDKN2A encoding p16INK4a." (PMID 25092922, 2014). "Interestingly, restoring BCL2L11 reversed these effects, confirming its function as a tumor suppressor epigenetically silenced by miRNA activity." (PMID 40558831, 2025).
tumor (continued). "Of note, several negative regulators of anti-tumor responses were down-regulated in CUL5 KO cells including exhaustion-associated biomarkers (NR4A2, PDCD1 and CD160), myeloid-derived suppressive cell promoting cytokine CSF2, and pro-apoptosis factor BCL2L11." (PMID 38242867, 2024). "Therefore, when tumor cells resist apoptosis signals by upregulating BCL2L11, AKT1, and LMNA genes, they simultaneously exhibit reduced responsiveness to lipid receptor activity." (PMID 39381047, 2024). "Therefore, miR-106a overexpression correlated with tumor growth, migration, and invasion as the result of BCL2L11 downregulation in EMC tumor cells." (PMID 37627777, 2023). "Histone acetylation in BCL2L11 is responsible for the apoptosis of CTCL tumor cells." (PMID 35408897, 2022). "This indicates that enhancer control of BCL2L11 may be important in other contexts and may be a target for disruption in tumour cells." (PMID 27490482, 2016). "In addition to p16INK4a, another well-studied example of EBNA-3-mediated epigenetic suppression is Bim/BCL2L11 tumor suppressor expression." (PMID 27886133, 2016). "In patients with ALCL, the BIM is encoded by BCL2L11, which is suppressed due to the recruitment of the SIN3a–HDAC1/2 corepressor complex, and treatment with the deacetylase inhibitor trichostatin This reverses this suppression and enhances tumor cell apoptosis." (PMID 35408897, 2022). "Giulia-Romano found that the increased expression of miR-494 lead to the Tumor necrosis factor Related Apoptosis-Inducing Ligand (TRAIL) resistance in NSCLC via down regulation of BCL2L11, which may inhibit the apoptosis and promote the tumorigenicity of tumor cells." (PMID 29416694, 2018). "Interestingly, some of them function as tumor suppressors (e.g. BCL2L11, MXD1, WWOX, BNIP3L, and DMTF1) or are candidate tumor suppressors having anti-proliferative properties and DNA repair abilities (e.g. LRRC2, RPA4, PPP6R1, SPEN, RAP1GAP and CISH) (see discussion section)." (PMID 26918450, 2016). "In addition to modifying HAT and HDAC activities, EBNA-3 proteins precisely EBNA-3A and -3C were also shown to recruit DNA-methyltransferase (DNMT) activity in order to suppress Bim (BCL2L11) tumor suppressor expression in Burkitt's lymphoma cells (discussed in more details in later section)." (PMID 27092119, 2016). "Thus, the DUSP5/DUSP5P1 system could be responsible for regulation of BCL2L11 leading to inhibition of apoptosis in these tumor cells." (PMID 24651368, 2014). "In EBV-infected B-cells, IRF4 and BATF jointly repress tumor suppressors like PRDM1 and BCL2L11, thereby promoting transformation." (PMID 40313738, 2025). "The level of miR-19b is upregulated by the activation of the EGFR/AKT pathway, which inhibits the apoptosis pathway in NSCLC cells via targeting Bcl2L11 and PPP2R5E, thereby promoting the proliferation of tumor cells." (PMID 38216965, 2024). "BCL2L11 and AKT1 have been confirmed in multiple studies to resist apoptotic signals, serving as key players in tumor cells’ defense against the immune system." (PMID 39381047, 2024). "Among them, 6 genes including BCL2, BCL2L11, BAD, CASP7, CASP9, and CYCS expression reduced in tumor tissue compared to normal according to meta-analysis studies and RNA-seq TCGA data." (PMID 33292233, 2020). "Of interest, our analysis highlighted that, independently of the nature of malignant B cells, the pro-apoptotic BH3-only BCL2L11 and PMAIP1 are deeply repressed in tumor niches, suggesting a central role of the microenvironment in their regulation." (PMID 30666297, 2018). "Of interest, our analysis highlighted that, independently of the nature of malignant B cells, the pro-apoptotic BH3-only BCL2L11 and PMAIP1 genes were deeply repressed in tumor niches." (PMID 30666297, 2018). "The wound healing assay reveals that inhibiting either BCL2L11 or CDH9 will enhance the migration of cell lines, which provides evidence that these two genes are suppressors of tumor metastasis." (PMID 28855549, 2017).
tumor (continued). "In general, epithelial cell lines and tumors were associated with cancer stem cell markers (CD24, ALDH1A1, and PROM1), markers of tumor aggressiveness (MYCL1 and ASCL1), and markers of apoptosis (BCL2 and BCL2L11)." (PMID 28212573, 2017). "Eventually, up-regulation of these miRNAs impaired the TGFβ tumor suppressor pathway through interfering with the expression of CDKN1A (p21Waf1/Cip1) and BCL2L11 (Bim)." (PMID 26956882, 2016). "A decisive tumor‐suppressive role of FoxOs is present upon cellular damage, which results in FoxO‐mediated induction of pro‐apoptotic genes such as TNFSF10 (TRAIL), FASLG (FasL), BCL2L11 (BIM), or BBC3 (PUMA)." (PMID 39533662, 2025). "Furthermore, we analyzed the expression levels of UHRF1 and BCL2L11 in the TCGA_CHOL cohort and confirmed that UHRF1 and BCL2L11 were highly expressed in tumor tissues than in the adjacent normal tissues." (PMID 35449153, 2022). "In lung cancer, overexpression of miR-17 and miR-19 affects the expression of HIF1A, PTEN, BCL2L11, CDKNA, and TSP1, enhancing tumor growth by increasing the permeability of blood vessels, inducing hypoxia, increasing proliferation, inhibiting apoptosis, and stimulating tumor cell migration." (PMID 33803617, 2021). "In addition, our bioinformatics analysis revealed that miR-20a regulated several cancer-related genes, particularly tumor suppressor genes, such as PTEN, BCL2L11, FBXO31, and DUSP2." (PMID 33125430, 2020). "In the colon, up-regulated miR-17-92a promotes neoplasia through various pathways, e.g. miR-18a and miR-19 directly repress TSP-1 and CTGF, respectively, to promote angiogenesis and miR-92a down-regulates BCL2L11 expression thereby reducing apoptosis." (PMID 26463716, 2015).
cancer (115 papers, 2005 to 2026). A tumor composed of atypical neoplastic, often pleomorphic cells that invade other tissues. "Taken together, our data suggest that inhibition of YAP/TAZ synergizes with KRAS G12C inhibitors to induce robust apoptosis in cancer cells via upregulating the expression of proapoptotic genes such as BCL2L11, BMF, and PUMA." (PMID 39704172, 2024). "The therapeutic strategy of reactivating the expression of BCL2L11 (BIM) in cancer cells, in order to induce their apoptosis, has been explored for decades in previous studies." (PMID 36229595, 2022). "In previous studies, overexpression of BCL2L11 and BAX have been associated with higher sensitivity of cancer cells to gefitinib." (PMID 35216325, 2022). "One gene in particular, BCL2L11, contained a single hyperDMR that spanned both the gene’s promoter and an active enhancer in both cancer types." (PMID 34021236, 2021). "In fact, based on the Cancer Cell Line Encyclopedia, DLBCL lines express the highest mRNA expression level of BCL2L11/BIM compared with other cancer cell lines." (PMID 30404918, 2018). "A common deletion polymorphism of the gene Bcl-2 like protein 11 (BCL2L11, BIM) has been reported to cause tyrosine kinase inhibitors (TKIs) resistance in several malignant tumors." (PMID 29228749, 2017). "To the best of our knowledge, we believe that we are the first to verify that gene BCL2L11 is a suppressor of cancer metastasis." (PMID 28855549, 2017). "We selected two predicted targets of the miR-106b~25 cluster, cyclin-dependent kinase inhibitor 1A (p21WAF1/CIP1) and BCL2-like 11 (BIM), based on protein function and relevance of these proteins in cancer." (PMID 27351222, 2016). "The obvious inhibition of BCL2L11 is surely to contribute to decreased apoptosis and accelerated proliferation of cancer cells, and is resulted from the high expression of miR-24." (PMID 26758252, 2016). "Although it has been recognized that anti-apoptotic members of BCL-2 family (e.g., BCL2L1/BCL−xL), inhibit autophagy and apoptosis of cancer cells, little known is about the biological function of pro-apoptotic members (e.g., BCL2L11/Bim, BID)." (PMID 26517093, 2015). "From the perspective of autophagy, the downregulation of BCL2L11 can improve the death threshold of cancer cells through two mechanisms, thus promoting their drug resistance: the direct inactivation of apoptotic signaling cascade and the induction of cytoprotective autophagy." (PMID 39239646, 2024). "Moreover, the transcripts of the following notional cancer genes were significantly increased: Rbl1, Bcl2l11, Map3k2, Bcl6, Ppp1, Cdc42, and Ppp2." (PMID 38731901, 2024). "Two of the genes evaluated showed elevated protein expression in tumors from IL-6-deficient Eμ-myc mice: BIM [BCL2L11], a BCL-XL and BCL2 interacting mediator of cell death, and PTEN, a phospholipid phosphatase and tumor suppressor gene mutated in many human cancers." (PMID 33651821, 2021). "Interestingly, the proapoptotic BH3-only protein BIM (encoded by BCL2L11), which is a master regulator of cell death in cancer cells, is a relevant target of miR-19b in spontaneous and TNFα/ActD-induced apoptosis." (PMID 29455644, 2018). "Therefore, BCL2L11 acts as a cancer suppresser in GC; its dramatic down-regulation contributes to the reduced cell death and fast cell growth rate in cancer." (PMID 26758252, 2016). "Although the role of BCL2L11 has been reported in these biological processes, the information that BCL2L11 regulates cell growth and apoptosis in cancer, especially in gastrointestinal tumors, remains largely unknown." (PMID 26758252, 2016). "Three highly complementary studies published in this issue of PLoS Medicine address this important question and identify the proapoptotic molecule BIM (BCL2-interacting mediator of cell death, also called BCL2-like 11) as critical mediator of EGFR TKI-induced cell death in EGFR-driven cancer." (PMID 17973575, 2007).
cancer (continued). "Alternative splicing was pervasive, with recurrent high-magnitude events at cancer-relevant loci including GJA1 (SE), NF2 (A3/A5), LIN37 (A5), ECT2 (A3/A5), BCL2L11 (A3), UQCRH (A5), CSE1L (A3), BROX (A3), and multiple ZNFs." (PMID 41952686, 2026). "Certain mRNAs, such as Serpine1, have been found to trigger the degradation of miR-30b/c, while BCL2L11 promotes miR-222 degradation, enhancing BIM-induced apoptosis in cancer cells." (PMID 41154621, 2025). "Treatment of BBC and GBM cancer cells with AS1842856 led to increases in FAS (FAS cell surface death receptor) and BIM (BCL2L11) gene expression, as well as increased positivity for markers for apoptosis such as annexin V and propidium iodide." (PMID 36602390, 2023). "One group of identified target genes is formed by the apoptosis regulators BIN1, BCL2L11 (BIM), BCL-XL, ICAD, and MCL1, with SRSF1 overexpression in cancer cells promoting the formation of their respective antiapoptotic splice variants." (PMID 26273603, 2015). "EP300, ISGF3G, STAT1, and STAT3 are up regulated in 8/13 of cancer models, while ATM, BAX, BCL2L11, HTATIP2, LGALS3, MAPK1, and TP73L are down regulated in half of cancer models." (PMID 19402918, 2009). "BCL2L11 (also known as BIM) is an essential proapoptotic BH3-only protein that initiates the intrinsic apoptotic pathway and plays an important role in promoting apoptosis in many cancer cells." (PMID 38690279, 2024). "It has been reported that the decreased expression of miR-92 may decrease cancer cell proliferation and increase the levels of PTEN, BCL2L11 and CDKN1A expression." (PMID 24137349, 2013). "Hence, both BCL2L11 and CDH9 are highly likely to be suppressors of cancer metastasis, which agrees with our hypothesis." (PMID 28855549, 2017). "Although BCL2L11 is well known to mediate cell apoptosis, its expression pattern and the biological role in cancer have not been detailedly described yet." (PMID 26758252, 2016). "Moreover, the expression pattern and function of BCL2L11 in cancer, especially in GC, have not been explored yet." (PMID 26758252, 2016). "Furthermore, USP27x is present in complex with BCL2L11 and BTRC, which facilitates BCL2L11 degradation in response to mitogen-activated protein kinase (MAPK)/extracellular signal-regulated kinase (ERK) signaling and sensitizes human cancer cells to chemotherapeutic drugs." (PMID 36551253, 2022).
infection (21 papers, 2010 to 2025). The state of being infected such as from the introduction of a foreign agent such as serum, vaccine, antigenic substance or organism. "Both genes are differentially expressed when comparing wt versus LPKO EBV infected B cells 48 h post infection reflecting the loss (BIRC3) and gain (BCL2L11) of intragenic interactions." (PMID 39747661, 2025). "It is known that BIRC3 transcription is significantly repressed already 48 h after infection of naive B cells with wild-type EBV whereas transcription of BCL2L11 is induced after 24 h to become repressed later starting at day 3 post infection." (PMID 39747661, 2025). "EBNALP represses BCL2L11 early during infection, as EBNA3C is expressed later following EBV infection." (PMID 39747661, 2025). "For example, a knockout mouse model of the Morrbid gene (myeloid RNA regulator of BCL2L11 induced cell death) resulted in decreased monocytes, increased apoptosis, and increased sensitivity to infection." (PMID 37446105, 2023). "By targeting INK4a (and BCL2L11) EBV has evolved an effective countermeasure to oncogenic stress triggered by the early stages of infection." (PMID 23436997, 2013). "Both RUNX1 and BCL2L11 undergo abnormal alternative splicing during infection." (PMID 39272372, 2024). "Similarly, there were increases in abundance after death of genes that are required for innate (Laao, Tox2) and adaptive immunity (Ms4a17, Usp18) and increased levels of the apoptotic genes (Fosb, Bcl2l11) that are normally activated by infection and injury." (PMID 36982814, 2023). "It is hypothesized that during infection of bovine mammary epithelial cells by S. agalactiae, genes such as tsf, prfB, and infC, which are involved in RNA binding, infiltration of host cells, and disruption of lncRNA targeting of RUNX1 and BCL2L11." (PMID 39272372, 2024).
bacterial infection (2 papers, 2024). "This indicates that under continuous bacterial infection, alternative splicing of BCL2L11 is affected, altering its splicing form and resulting in changes in BCL2L11 conformation." (PMID 39272372, 2024).
gynecologic tumor (1 paper, 2022). "Some of the differential NRGs are unique to a particular gynecologic tumor, such as BCL2L11 and OTULIN in CESC, MAP3K7 in OV, TLR2 in UCS." (PMID 36357839, 2022).
metabolic disease (1 paper, 2025). A congenital disorder (due to inherited enzyme abnormality) or acquired (due to failure of a metabolically important organ) disorder resulting from an abnormal metabolic process. "In metabolic diseases, lean adipose tissue macrophage-derived exosomes (ExosLean) deliver miR-222-3p to target the inflammatory factor Bcl2l11/Bim, promoting macrophage polarization toward a reparative M2 phenotype in diabetic wounds and accelerating tissue healing." (PMID 41459510, 2025).
neurological disorders (1 paper, 2025). "In neurological disorders, miR-221 emerged as a neuroprotective factor in Parkinson’s disease (PD): the PD-linked protein DJ-1 upregulates miR-221 via the MAPK/ERK pathway, which then represses pro-apoptotic proteins (BCL2 like 11(BIM), BMF) to protect dopaminergic neurons from oxidative stress." (PMID 41369385, 2025).
BCL2L11 also shares sentences with these, for which no sentence is quoted: diabetes (7 papers); hepatocellular carcinoma (6); lung adenocarcinoma (5); mantle cell lymphoma (4); myocardial infarction (3); small cell lung carcinoma (3); asthma (2); cervical carcinoma (2); chronic periodontitis (2); Eμ (2); HIV-1 infection (2); kidney diseases (2); liver cancer (2); multiple sclerosis (2); non-Hodgkin lymphoma (2); renal carcinoma (2); sarcoma (2); Stroke (2); acute leukemia (1); adenocarcinoma (1); Allergy (1); alopecia areata (1); alveolar soft part sarcoma (1); anaemia (1); anaplastic large cell lymphoma (1); atopic dermatitis (1); atrial fibrillation (1); Atrophy (1); autosomal dominant polycystic kidney disease (1); B-cell acute lymphoblastic leukemia (1).